LAG3 (lymphocyte activating 3)
Diseases named in the same sentence as LAG3 in open-access papers (continued):
Sharing a sentence is not in itself a finding about the gene and the disease.
tumor (continued). "Next, we compared the levels of tumor-infiltrating B cells, T cells and their subsets, and NK cells expressing PD-1, TIM-3, LAG-3, TIGIT, and ICOS between patients with advanced and early stage CRC." (PMID 33477864, 2021). "LAG-3 is, along with PD-1/PD-L1 and CTLA-4, a promising target in cancer immunotherapy, since it plays a pivotal role in anti-tumor immunity." (PMID 33925565, 2021). "The inhibitory molecules (LAG-3 and PD-1) expression in CD8+ T cells from peripheral bloods of NC (n = 9), peripheral bloods of GC patients (n = 11), and tumor-residency of GC patients (n = 11) was also measured by flow cytometry." (PMID 34620075, 2021). "Activation in the presence of CAFs induced phenotypic changes in both CD8+ and CD4+ T cells with upregulation of co-inhibitory receptors PD-1, Tim3 and LAG-3 as well as CD39 resulting in a phenotype resembling that of tumor infiltrating T cells." (PMID 34290905, 2021). "Tumor cells use inhibitory signaling pathways in the immune system, such as the PD-1/PD-L1, CTLA-4, LAG-3, Tim-3, and CD160 signaling pathways, to inhibit the function of TILs in the TME, resulting in tumor immunosuppression." (PMID 34513820, 2021). "Recently, in another study, LBL-007, a new anti-LAG-3 IgG4 antibody, was assessed in mice with CRC at a dose of 10 mg/kg twice a week for three weeks; it was found to inhibit tumor growth." (PMID 34572263, 2021). "Immune checkpoints were one of the reasons for tumor immune escape, we examined the relationship between immune-related genes and major immune checkpoints (PD-1, PD-L1, CTLA4, LAG3, and VSTM3)." (PMID 35252217, 2021). "Eight tumor-related immunosuppressive molecules, CD274, CTLA4, HAVCR2, LAG3, PDCD1 (PD1), PDCD1LG2, SIGLEC15, and TIGIT, had higher expression in HNSCC tumor tissues compared with HNSCC normal tissues." (PMID 34917682, 2021). "Next, by applying hierarchical clustering to the 105 ccRCC tumour samples based on the normalized LAG-3-, TIM-3-, and TIGIT-positive cell densities in each tumour, we successfully identified three groups with distinct IR levels." (PMID 34545095, 2021). "Oxysophocarpine also enhances the therapeutic effect of anti-LAG3 mAb in HCC, promoting the function and cytotoxicity of tumor-related CD8+ T cells." (PMID 35111155, 2021). "Within the tumor-infiltrating CD4_4 cluster, we observed increased expression of the Th1 driver TBX21 (T-bet), activation marker LAG3 and NR4A2 and cytokine expression." (PMID 33504936, 2021). "In terms of LUAD patients, most biomarkers, including IDO1, CTLA4, LAG3, CD40, TNFRSF18, TIGIT, and TNFSF14, were significantly increased in tumor tissues with high B cell abundance compared with that of low B cell group." (PMID 34422829, 2021). "Inhibition of LAG-3 can lead to recruitment of cytotoxic CD8+ T cells and has shown to restrain tumor growth in in vivo models." (PMID 34277428, 2021). "LAG-3+ Tregs in the TME secrete high levels of immunosuppressive cytokines, IL10 and TGFβ, which act to dampen the anti-tumour immune response and magnify Treg activity." (PMID 33401460, 2021). "Here, we focused on the immunological reaction of tumor infiltrating lymphocytes, as the TME regulate immune-checkpoint proteins, such as PD-1, CTLA-4, Tim-3, and Lag-3." (PMID 34564709, 2021). "As such, it would be of interest to further study the effect of PRAME tumour expression on other immune checkpoints such as TIM‐3 and LAG‐3 within the context of immune checkpoint blockade." (PMID 34612587, 2021). "The best overall response rate and progression-free survival (PFS) were analyzed depending on the expression of CD68, CD163, PD-1, LAG-3, TIM-3, CTLA-4, TIGIT, CD163/c-maf in the tumor microenvironment in primary and sequential biopsies." (PMID 34830831, 2021). "By blocking LAG-3 and PD-L1 simultaneously, FS118 can act as a bridge for TILs to perforate PD-L1-positive tumor cells." (PMID 34514097, 2021).
tumor (continued). "Tumor cells produce soluble molecules, such as IDO, PEG2, TGF-β, and a series of membrane molecules, including PD1, PD-L1, LAG3, TIGIT, and CTLA4." (PMID 34177887, 2021). "According to the data in TCGA tumor samples, the copy numbers of DHX37 were positively correlated with TIM3, LAG3 and NCOR2, while they were negatively correlated with PD-L1, RGS16 and TOX." (PMID 33490273, 2021). "We investigated the levels of tumor-infiltrating B cells, T cells and NK cells compared to normal tissue milieu and established the expression profiles of PD-1, TIM-3, LAG-3, TIGIT, and ICOS on the different tumor-resident lymphoid populations." (PMID 33477864, 2021). "For example, CD4+ naive T cells (cluster 0/cluster 2) located at the core of the tumor expressed more immune checkpoint molecules, such as CTLA4, LAG3, HAVCR2, and TNFRSF9/CD137." (PMID 34513820, 2021). "Tumor growth is accompanied by immune escape, which is facilitated by immune checkpoint molecules, such as CTLA-4, PD-1/PD-L1/2, and LAG3." (PMID 34768716, 2021). "We also identified a subtype of proliferative T cells (Cluster 7 with high KI67 expression) which displayed both effector T-cell features (e.g., GZMA) and dysfunctional markers such as LAG3, TIGIT, and PD-1, indicating compromised tumor cytotoxic activity." (PMID 33144684, 2021). "It has been suggested that overexpression of immunosuppressive molecules (e.g., CTLA4, LAG3, and PD1) and immunosuppressive cells (e.g., Tregs) are involved in tumor immune escape and contribute to tumorigenesis and progression." (PMID 34490047, 2021). "Considering the vital role of immune checkpoint molecules (PD-1, PD-L1, LAG3 and CTLA-4) in tumor immune microenvironment, we analyzed the expression of these molecules in two TNF patterns." (PMID 34691075, 2021). "When blocking LAG-3 one would expect to enhance the functioning of MHCII+ APCs, resulting in a better anti-tumor immune response." (PMID 33466653, 2021). "Fresh cells tumor microenvironment analysis included phenotypic characterization of their T cell surfaces immune checkpoint markers PD-1, PD-L1, ICOS, TIM-3, LAG-3, 41-BB and BTLA." (PMID 34771650, 2021). "We present a comprehensive overview of the role of LAG3/FGL1 in cancer, suggesting novel anti-tumor therapy strategies." (PMID 35111155, 2021). "In addition, long-term exposure of tumor antigens to Th1 cells and other T cell subtypes may promote the expression of inhibitory receptors, such as PD-L1, lymphocyte activation gene 3 protein (LAG-3), and T-cell immunoglobulin (Ig) domain and mucin domain protein 3 (TIM-3)." (PMID 35111169, 2021). "Expression of LAG-3 is triggered by TCR or cytokine stimulation and it interacts as a ligand of the MHC II molecule expressed on APCs and tumor cells." (PMID 34356899, 2021). "As we found a positive association between LAG3 expression and its ligands and confirmed the association between LAG3 and loss of BAP1 expression/the presence of monosomy 3, we wondered whether expression of LAG3 ligands would similarly show associations with high-risk tumour characteristics." (PMID 34503258, 2021). "In this context, our results provide new insights about LAG-3 expression dysregulation in CLL and its role promoting tumor escape." (PMID 33925565, 2021). "We also discovered that CD38 expression positively correlated with PD-1, CTLA-4, TIGHIT, GITR, LAG-3, and VISTA, indicating that upregulated CD38 levels in tumor microenvironment mediated ICI-resistance." (PMID 34211854, 2021). "We selected the markers of the immune checkpoint molecule (PD1, PD-L1, and LAG-3) and immune cell (CD3, CD4, CD8, and Foxp3) as markers of the tumor microenvironment." (PMID 34484468, 2021). "Here, we analyze the expression of VISTA, LAG3, IDO, and TIM3 on tumor-infiltrating lymphocytes (TILs) and its impact on patient survival." (PMID 34072549, 2021).
tumor (continued). "We also observed increased expression of B7-H3, Bcl-2, CTLA4, LAG3, Tim-3, PD1, PDL1 and STING in the second sample compared with the first sample (and some differences appear contingent upon the tumor or stroma compartment)." (PMID 34838031, 2021). "Treg cells also express lymphocyte activation gene 3 (LAG-3), which inhibits the induction of tumor-specific T cell responses by suppressing DC activation via interaction with MHC class II." (PMID 34885241, 2021). "PD1, TIM3, LAG3, and CTLA4, expressed on the surface of CD4+ and CD8+ T cells, indicate the occurrence of tumor immune escape phenomenon in PVNS pathogenesis." (PMID 34248943, 2021). "The main tumor extrinsic mechanism for AR is the upregulation of other immune checkpoints, such as TIM-3, LAG-3, and VISTA." (PMID 34194441, 2021). "In patients with high-grade serous carcinoma, NanoString analysis of tumor tissues has indicated that recurrent tumors acquire a more inflamed phenotype with increased expression of TIGIT, CTLA4, Lag-3, and Tim-3 compared to primary tumors." (PMID 33670993, 2021). "Studies have shown that tumor-infiltrating lymphocytes have elevated levels of TIGIT co-expressed with PD-1, LAG-3 and TIM-3 suggesting a role in tumor progression." (PMID 34268109, 2021). "For cluster 22, the cells were defined through the expression of CD8+, CD39+, CD223+ (Lag-3), CD62L−, GrzB+, and IFNγ, indicating activated CD8+ T cells capable of tumor killing function." (PMID 34912335, 2021). "Lymphocyte activation gene-3 (LAG-3) belongs to the immunoglobulin superfamily and is expressed on tumour infiltrating lymphocytes (TILs), NK cells, B cells and DCs." (PMID 33995362, 2021). "Future studies determining the E3 ligases that mediate LAG-3/MHC-II expression and function regulation can help elucidate the role of E3 ligases in tumor immune response and develop related targeted drugs to strengthen immune surveillance." (PMID 34943817, 2021). "To examine if tumor-infiltrating MAIT cells have an exhausted phenotype, we analyzed their expression of the surface markers PD-1, Tim-3, CD39, TIGIT, BTLA, and LAG3, which have all been used to identify exhausted conventional CD8+ T cells in tumors." (PMID 33885944, 2021). "For example, in mice with MC38 tumor, dual LAG-3/PD-1 coblocking synergism restricted the growth of MC38 and resulted in 80% tumor clearance in mice." (PMID 34447484, 2021). "Based on the exciting finding on the powerful value of LAG-3 as serum biomarker for predicting tumor response to TACE therapy, we continued to evaluate the prognostic significances of pretreatment serum levels of LAG-3 and PD-L1." (PMID 34691076, 2021). "First, we sought to apply an automated single-cell count for immunolabelled LAG-3, TIM-3, and TIGIT to 105 primary ccRCC tumour samples (i.e. COHORT 1)." (PMID 34545095, 2021). "Studies have reported that PD-1 and LAG-3 are co-expressed on CD4+, CD8+ and tumor-infiltrating T-cells." (PMID 34575943, 2021). "The percentage of OAC cells expressing LAG-3 in treatment-naïve, post-FLOT and post-CROSS tumour biopsy tissue was: 2.42 ± 0.4, 0.89 ± 0.3% and 3.29 ± 1.2%, respectively." (PMID 33765543, 2021). "FGL1 also inhibited the antigen-specific T cell response via LAG-3 in vitro and in vivo, and FGL1-KO enhanced T cell immunity and suppressed tumor growth in a mouse model." (PMID 33633363, 2021). "In contrast, the highly immunogenic CT26-HER2 tumor was recognized by the immune system and appeared to actively fight for its survival by adopting several strategies (CTLA-4, LAG3, PD1, and Tregs) that reverse the activity of the antitumor immune effectors." (PMID 34578328, 2021). "There have been a number of studies using CRISPR–Cas9 to knock out inhibitory receptors such as PD-1, LAG-3 and TIM-3 in cancer-specific T cells, leading to enhanced anti-tumour activity." (PMID 32708397, 2020).
tumor (continued). "After “rest” away from the tumor microenvironment, the expression levels of inhibitory receptors (e.g., PD1, TIM3 and LAG3) decreased dramatically." (PMID 33292660, 2020). "Along with increased PD-1 expression, the upregulation of the lymphocyte activation gene 3 (LAG3) negatively affects the function of the CD8 + lymphocytes, greatly diminishing their cytotoxic activity against the tumor." (PMID 32691290, 2020). "37% (n = 89) of OPSCC presented with high numbers of CD8+ TILs in their tumor microenvironment (TME) and this was significantly correlated with LAG-3, TIM-3 and VISTA expression in the whole cohort (p < 0.001, p < 0.001, p = 0.007)." (PMID 33396515, 2020). "Tumor‐infiltrating lymphocytes express multiple immune checkpoint molecules (eg, PD‐1, CTLA‐4, TIM‐3, LAG‐3, and TIGIT)." (PMID 32077528, 2020). "LAG-3 (CD223) is mainly expressed on the surface of B cells, NK cells, tumor-infiltrating lymphocytes (TILs), and a subset of T cells." (PMID 32944390, 2020). "These humanized monoclonal antibodies target inhibitory receptors (e.g. CTLA-4, PD-1, LAG-3, TIM-3) and ligands (PD-L1) expressed on T lymphocytes, antigen presenting cells and tumor cells and elicit an anti-tumor response by stimulating immune system." (PMID 33162990, 2020). "Blockade of this inhibitory signal can promote T cell mediated tumor cell death and activate TILs in CRC typically express high levels of LAG3, which make this a promising therapeutic target." (PMID 32748171, 2020). "We examined the expression of the exhaustion markers PD-1, LAG3, and TIM3 7 days after the first and third stimulations with LM7 tumor cells." (PMID 33148882, 2020). "In this study, high ectopic LAG‐3 expression was observed in 61.5% of the NSCLC patients, and LAG‐3 expression was also observed in tumor metastatic lymph nodes." (PMID 32077528, 2020). "And even, downregulation of three inhibitory receptors (PD1, TIM3 and LAG3) simultaneously on CAR T cells show increased tumor infiltration and durable tumor control." (PMID 33292660, 2020). "There were also some, but fewer, triple-positive and PD-1+LAG-3+ cells in the OVA Tet− subset, presumably those cells specific for other tumor antigens." (PMID 33207844, 2020). "In the Sa1N tumor model, dual blockade of LAG3 and PD1 achieved tumor clearance in 70% of mice compared with 20% survival in mice receiving anti-PD1 monotherapy." (PMID 33488573, 2020). "The capability of Gal-3 to bind activated antigen-committed CD8+ T cells is only possible in the tumor microenvironment through Gal-3 binding to LAG-3, and thus LAG-3 expression is necessary for galectin-3-mediated suppression of CD8+ T cells in vitro." (PMID 32408492, 2020). "Mice treated with pembrolizumab showed an escalation of exhausted T cells expressing TIM-3, and LAG-3 in tissues, higher levels of several human cytokines in plasma and high densities of FoxP3+ regulatory CD4+ and CD8+ T cells in the tumor microenvironment." (PMID 33511078, 2020). "The most frequent immune targets in the CD8+ T cells from the tumor microenvironment, in descending order, of newly diagnosed patients with GBM were A2aR > PD-1 > CD39 > TIGIT > LAG-3 > CTLA- 4 > BTLA > CD160 > CD73 > KIR > TIM3." (PMID 32721947, 2020). "Lymphocyte-activation gene 3 (LAG-3, CD223) and T cell immunoglobulin and mucin domain 3 (TIM-3) are coexpressed with PD-1 on tumor-infiltrating lymphocytes." (PMID 33121189, 2020). "DPTs at tumor sites secrete more IL-10, IDO, and TGFβ and express higher levels of immune checkpoints PD-1, LAG-3, and TIM-3 than Tregs, CD4+ T cells and CD8+ T cells." (PMID 32457755, 2020). "We also identified three CD8 T cell subsets: exhausted CD8 (CD39+ Tim3+ Lag3+ CD8+), classical CD8 (CD3+ CD8+ CD44+ MHCII+ Tim3− Lag3− CD25−) and tumor-reactive CD8 (CD39+ CD103+ CD8+)." (PMID 32764562, 2020). "LAG-3 is expressed on B, T, and NK cells and binds to MHC class II molecules and L-SECtin bearing tumor cells." (PMID 32610578, 2020).
tumor (continued). "PD-1, TIM-3, CTLA-4, LAG-3, and CD244 mRNA levels were relatively similar amongst the different grades of tumor budding." (PMID 32393998, 2020). "LAG3, TIM3, ICOSLG, VISTA, GITR and CD40 were all detected in a majority of the 20 tumor subcohort over an abundance range between 10- and 40-fold." (PMID 32555523, 2020). "Tregs combined with CTLA4, LAG3, and TIGIT related to a worse prognosis in RCC exerted immunosuppressive effects, favoring tumor escape from the activity of a variety of antitumor immune effector cells." (PMID 32252440, 2020). "Moreover, antibodies against PD-L1, TIM-3, or LAG3 restore responses of HCC-derived T cells to tumor antigens, and combinations of these antibodies have additive effects, suggesting that blocking those signaling pathways might benefit patients with primary liver cancer." (PMID 32408492, 2020). "Lymphocyte-activation gene 3 (LAG-3, CD223) is a transmembrane protein reported to be primarily expressed on tumor-infiltrating T cells." (PMID 32787882, 2020). "Dual blockage of LAG3 and PD-L1 with monoclonal antibodies led to increased CD4- and CD8-positive TILs and tumor clearance compared to monotherapy in mice models." (PMID 32232506, 2020). "The emerging treatment modality of immunotherapy targets immune checkpoint molecules including PD-1 and its ligand PD-L1, CTLA-4, LAG-3, and TIM-3 to enhance the host immune response against tumours, and to limit the growth and progression of cancer cells." (PMID 32708945, 2020). "Even though our data support a functional role for CD4+ T cells in effective anti-parasite immunity, the fibrinogen-like protein 1 (FGL-1) appears as a major ligand of LAG-3 that works independently of MHC-II, and inhibits T cell-mediated anti-tumor immunity." (PMID 33519801, 2020). "In MHCII+ tumor microenvironments, the infiltration of CD4+ T cells increases and LAG3 (an MHCII inhibitory receptor)-induced TIL expression increases, thereby limiting antigen presentation and promoting resistance to anti-PD-1 therapy." (PMID 32000802, 2020). "Tumor-infiltrating lymphocytes are in several cases found tumor-reactive, but expression of the immune checkpoint receptors TIM-3, TIGIT and LAG3 is also abundant." (PMID 32313009, 2020). "T lymphocytes that infiltrated the tumor in the final phase of the disease showed higher expression levels of chronic activation markers (PD1, LAG3), while ligands for PD1 were significantly overexpressed in the tumor microenvironment at progression." (PMID 32354143, 2020). "In other tumor models, synergism involving PD1 and LAG3 was reported, suggesting the dual blockade of LAG3 and PD1 has sufficient efficacy for the treatment of various tumors." (PMID 33488573, 2020). "LAG-3 inhibitors hinder the interaction of LAG-3 with MHC class II and then repair the activity of effector T cells to kill tumor cells." (PMID 32195194, 2020). "In the context of cancer, LAG‐3 has been shown to limit both the accumulation and effector function of CD8+ T cells in tumor tissue, and its elevated expression on tumor‐infiltrating Tregs correlates with enhanced immunosuppressive activity by these cells." (PMID 32508018, 2020). "Co-culture of DLBCL cell lines with primed T cells in the presence of anti-LAG-3 and anti-TIM-3 induced potent dose-dependent increments in in vitro cell death, suggesting the anti-tumor activity of these antibodies." (PMID 32751706, 2020). "On the other hand, Tils in the tumour microenvironment, especially CD8+ T cells, also express a large number of other immune checkpoint molecules, such as LAG-3, TIM-3, TIGIT, VISTA, B7-H3, and BTLA." (PMID 32775040, 2020). "Because of reduced signaling of these regulators, tumor-residing CD8+ T-cells upregulate checkpoint molecules, such as PD-1, CTLA-4, LAG-3, and TIM-3, reflecting the exhausted state of these cells." (PMID 33072086, 2020). "LAG3 principally interacts with MHC-II molecules expressed on the surfaces of antigen presenting cells and tumor cells." (PMID 33488573, 2020).